GFAP (glial fibrillary acidic protein)
Diseases named in the same sentence as GFAP in open-access papers (continued):
Sharing a sentence is not in itself a finding about the gene and the disease.
ocular hypertension (continued). "Immunolabeling of retinal whole mounts demonstrated a prominent drop in the ocular hypertension-induced IκKβ labeling of GFAP+ astroglia in GFAP-IκKβ mice compared to IκKβf/f controls." (PMID 32859212, 2020). "Although the overall density of GFAP+ cells remained unchanged, astroglial cells exhibited a hypertrophic morphology in ocular hypertensive eyes (relative to saline-injected normotensive controls)." (PMID 32859212, 2020). "We next studied transgenic effects on astroglial responses to ocular hypertension by analyzing the quantitative measures of immunolabeling for GFAP." (PMID 32859212, 2020). "Similarly, ocular hypertension-induced increase in the percentage GFAP coverage, reflecting the size and density of individual cells, slightly decreased with astroglial cFLIP or cFLIPL deletion." (PMID 38824526, 2024). "In addition to the decreased inflammatory activity of astroglia after IκKβ deletion, we also detected a decrease in the ocular hypertension-related microglial response in GFAP-IκKβ retinas." (PMID 32859212, 2020). "Therefore, co-expression of GFAP and glutamine synthetase (GS) was described in the end-feet and processes of MCs after ocular hypertension." (PMID 32106630, 2020). "However, ocular hypertension-induced glial inflammatory responses exhibited a prominent reduction by tamoxifen-induced cre/lox-based deletion of IκKβ in GFAP-expressing astroglia." (PMID 32859212, 2020). "Interestingly, besides these transgenic effects on the ocular hypertension-induced astroglial GFAP response, some effects were also detectable on the immunolabeling pattern of reactive microglia." (PMID 32859212, 2020). "However, despite a prominent reduction of PERG amplitude after 12 weeks of ocular hypertension in IκKβf/f mice, it was preserved in ocular hypertensive eyes of GFAP-IκKβ mice." (PMID 32859212, 2020). "Therefore, in an acute model of ocular hypertension (perfusion of the anterior chamber of eye with saline solution), an increase in the number of GFAP-positive astrocytes throughout the superficial layers of the contralateral SC was found." (PMID 32106630, 2020). "Despite a prominent increase in the intensity and the coverage of GFAP immunolabeling with ocular hypertension, both of these imaging parameters were decreased (approximately 56% and 48%, respectively) in ocular hypertensive GFAP-IκKβ retinas relative to ocular hypertensive IκKβf/f controls." (PMID 32859212, 2020). "Tissue immunolabeling supported increased production of this pro-inflammatory cytokine in GFAP-labeled astroglia in ocular hypertensive eyes; however, the ocular hypertension-induced TNF-α immunolabeling was prominently decreased in GFAP-IκKβ retinas compared to ocular hypertensive IκKβf/f controls." (PMID 32859212, 2020). "Thus, GFAP-labeled astroglia survived IκKβ deletion over the 12 weeks of experimental period with ocular hypertension and exhibited decreased inflammatory activity as exemplified by decreased production of pro-inflammatory/pro-apoptotic cytokines, including TNF-α." (PMID 32859212, 2020). "Similar to previous studies, ocular hypertension induced pro-inflammatory cytokine production in the retina and optic nerve of IκKβf/f control mice; however, pro-inflammatory cytokine titers were significantly lower in ocular hypertensive GFAP-IκKβ retinas and optic nerves." (PMID 32859212, 2020). "Similarly, upregulation of GFAP was observed in the Müller glial cells in the retina subjected to laser-induced ocular hypertension, while the astrocytes of the contralateral control eyes also exhibited an increase in GFAP and a change in the area covered by the astrocytes." (PMID 28381236, 2017). "In a mouse model of laser-induced ocular hypertension, there was upregulated expression of MHC-II and glial fibrillary acidic protein (GFAP) in the microglia of contralateral eyes." (PMID 26903709, 2016).
ocular hypertension (continued). "Not only GFAP/cFLIPL but also GFAP/cFLIP, lacking both isoforms, presented no induction of astroglial apoptosis at least at 12 weeks of ocular hypertension." (PMID 38824526, 2024). "This study analyzed neuroinflammatory and neurodegenerative outcomes of ocular hypertension in mice with or without cre/lox-based conditional deletion of IκKβ in glial fibrillary acidic protein (GFAP)-expressing astroglia (GFAP/IκKβ)." (PMID 34199494, 2021). "We therefore comparatively analyzed RGC and axon counts in GFAP-IκKβ and control eyes with or without ocular hypertension." (PMID 32859212, 2020). "In support of this observation, analysis of isolated Müller glia samples and the immunolabeling of retinas did not detect a significant decrease in the ocular hypertension-induced TNF-α production of Müller glia in GFAP-IκKβ mice." (PMID 32859212, 2020). "Immunoassays and immunolabeling of retina and optic nerve tissues presented reduced production of various proinflammatory cytokines, including TNFα, in GFAP/cFLIP and GFAP/cFLIPL relative to controls at 12 weeks of ocular hypertension with no detectable alteration in TUNEL." (PMID 38824526, 2024). "When we similarly analyzed TNF-α titers in isolated samples of retinal Müller glia, no statistically significant decrease was detectable in the ocular hypertension-induced production of TNF-α in GFAP-IκKβ mice compared to ocular hypertensive IκKβf/f controls (P = 0.06)." (PMID 32859212, 2020). "However, when we similarly analyzed the astroglia proteins obtained from GFAP-IκKβ mice, both the basal expression and ocular hypertension-induced upregulation of phospho-p65 were not detectable." (PMID 32859212, 2020).
retinal detachment (18 papers, 2009 to 2024). An eye emergency condition which may lead to blindness if left untreated. "For example, retinal detachment upregulates GFAP expression and concomitantly results in loss of GLUL expression and extensive derangement of glial and neuronal metabolite profiles." (PMID 21985191, 2011). "Even retinal detachment caused by a subretinal injection gave rise to activation of Müller glial cells as reflected by detectable GFAP expression levels at 28 days after injecting a balanced salt solution." (PMID 20808778, 2010). "Experimental retinal detachment caused an unequivocal upregulation of GFAP expression in Müller glial cells (arrowhead)." (PMID 19809515, 2009). "This is in line with previous findings in cats, in which BDNF attenuated GFAP expression following retinal detachment." (PMID 35955747, 2022). "The retinal astrocytes and Müller glial cells exhibit similar responses to injury, such as hypertrophy, upregulation of GFAP, vimentin, and GS, as observed in rat models of retinal detachment and retinitis pigmentosa." (PMID 28381236, 2017). "Müller cells seem to react very rapidly to an experimental retinal detachment by changing their expression profile, usually leading to a pronounced upregulation of GFAP expression." (PMID 28280483, 2017). "The next step would be a series of experiments in retinal detachment models looking at intraretinal GFAP and PDGFRα expression." (PMID 22966235, 2012). "Increased expression of GFAP and vimentin, indicative of increased reactivity, has been demonstrated in Müller glia in detached human retinas and experimental models of retinal detachment." (PMID 22966235, 2012). "GFAP is not only upregulated, but also actively involved in the morphological changes of Müller glial cells that follow experimental retinal detachment and age-related macular degeneration (AMD)." (PMID 20808778, 2010). "In our model of experimental detachment in murine retinas, Müller cells became reactive (as indicated by GFAP expression) and showed a decrease in potassium currents, similar as found in rabbit and porcine models of retinal detachment." (PMID 19809515, 2009). "This is a novel finding and maybe akin to GFAP expression being more globally distributed throughout the MG in chronic damage models of retinal detachment and blue-wave light exposure." (PMID 34790663, 2021). "However, it has been previously shown that the GFAP levels were higher in subjects with retinal detachment, proliferative vitreoretinopathy or epiretinal gliosis." (PMID 33627831, 2021). "However, in pathologically changed retinas, Müller cells become immunopositive for GFAP in retinal detachment and PVR." (PMID 22511850, 2012). "Beta-tubulin, vimentin, and glial fibrillary acidic protein (GFAP) may structurally reinforce the endfeet region of Müller cells and are upregulated throughout this cell type following retinal detachment and other forms of injury." (PMID 22065916, 2011).
Atrophy (17 papers, 2014 to 2026). Any weakening or degeneration, especially through lack of use. "Likewise, plasma GFAP was associated with atrophy of the left putamen (β = −0.275, p = 0.040), bilateral pallidum, right thalamus, and left hippocampus." (PMID 36922526, 2023). "In the wobbler mouse, which displays a muscular atrophy associated with motoneuron degeneration in early postnatal development, the glial fibrillary acidic protein (GFAP) is greatly increased in the spinal cord resulting in many changes in the number, distribution and morphology of astrocytes." (PMID 24465945, 2014). "Overall, APOE ε4 status significantly affected naming and memory scores, mesial temporal and entorhinal cortex atrophy scores, and glial fibrillary acidic protein concentration levels." (PMID 41085166, 2025). "In the DLB group, GFAP and NfL levels were higher in patients with more atrophy in medial temporal lobe (i.e. MTA) and frontal lobe (GCA-F), and a higher cerebrovascular lesion load (Fazekas)." (PMID 40847319, 2025). "As for cortical areas, NfL and GFAP were correlated with atrophy of the left lateral orbitofrontal cortex, right pars orbitalis, and right insula, but many correlations did not survive FDR correction." (PMID 36922526, 2023). "Both NfL and GFAP could aggravate the disease severity of MSA and contribute to the atrophy of MSA-susceptible areas." (PMID 36922526, 2023). "In a memory clinic cohort, we analysed plasma pTau181, pTau217, pTau231, respectively, GFAP, NfL, CSF pTau181, Aβ-PET scans, and MRI/CT visual read of atrophy." (PMID 39701863, 2025). "Our study characterized plasma p‐tau181, GFAP, and NfL in relation to clinical diagnosis, Aβ‐PET, and atrophy in a unique sample comprised of over 50% Hispanic older adults." (PMID 37671801, 2024). "Moreover, NfL levels were prognostic of atrophy in the WMV, whereas GFAP specifically prognosticate GM atrophy." (PMID 38234075, 2024). "In particular, the baseline GFAP levels were not predictive of the rate of WM or GM atrophy over the follow-up period." (PMID 37361716, 2023). "No brain atrophy was evident until animals reached at least until 3 months of age for GCLCfloxed X Iba1-Cre mice and 8 months of age for GCLCfloxed X GFAP-Cre mice." (PMID 36670138, 2023). "On the other hand, we observed no brain atrophy in GCLCfloxed X GFAP-Cre mice, suggesting that astrocytes could make compensation for loss of glutathione in neurons upon neuronal damage." (PMID 36670138, 2023).
breast carcinoma (17 papers, 2017 to 2025). "Here, we report a patient with GFAP astrocytopathy, which may occur in a paraneoplastic neurological syndrome associated with breast cancer." (PMID 37016352, 2023). "The higher GFAP intensity in MDA-MB-231 cells and SUM159PT cells co-cultured organoid suggested that these breast cancer cells induced a higher expression of GFAP, or they enhanced the transition of progenitors to GFAP+ astrocytes." (PMID 38951862, 2024). "As additional proof of inflammasome priming in astrocytes, human brain samples with breast cancer metastases were immunostained for IL-1β, which was also found to colocalize with GFAP and NLRP3 in the peritumoral regions." (PMID 37749707, 2023). "Metastatic resections were stained for breast cancer cells (anti-pan keratin) and activated astrocytes (anti-GFAP) and then regions of the tumor and stroma were similarly quantified to determine the cell densities across six separate patient samples." (PMID 35200398, 2022). "Brain metastatic clusters were located to the brain parenchyma, were associated with blood vessels and were surrounded by GFAP+ reactive astrocytes; all of these characteristics of breast cancer brain metastases." (PMID 29164052, 2017). "The aim of our study was to assess the dynamics of serum levels of NfL, GFAP, and tau in women exposed to adjuvant chemotherapy in early breast cancer and whether serum levels of NfL, GFAP, and tau predict and/or correlate with the severity of CIPN." (PMID 39099324, 2024). "In addition, NLRP3 inhibition proved to be protective against IL-1β upregulation in peritumoral astrocytes in the mouse breast cancer brain metastasis model, resulting in an approximately 75% decrease in the percentage of IL-1β- and GFAP-double-positive pixels." (PMID 37749707, 2023). "For the five FTD-Breast cancer comorbid genes (AKT3, GFAP, C4A, VDAC1, ADCYAP1R1), we analyzed the alterations in the genetic profiles among the different subtypes of Breast cancer." (PMID 37834358, 2023). "The differences in the histologic features and the GFAP-positive, cytokeratin-negative nature of the spinal neoplasm ruled out a metastasis from the patient’s previously diagnosed breast carcinoma." (PMID 34765976, 2021). "Here we assessed whether serum levels of neurofilament light (NfL) and tau (two neuroaxonal injury biomarkers) and glial fibrillary acidic protein (GFAP, a biomarker for astrocytic activation) correlate with the development of CIPN in the adjuvant setting of early breast cancer." (PMID 39099324, 2024). "When mice received Zfra4-10 or WWOX7-21 peptide alone followed by 4T1 breast cancer inoculation, these mice developed endogenous complex formation of WWOX with many target proteins, including ERK, C1qBP, NF-κB, Iba1, p21, CD133, JNK1, COX2, Oct4, and GFAP in the spleen, brain, and lung." (PMID 32764489, 2020).
demyelinating disease (17 papers, 2015 to 2025). A broad group of disorders that affect the myelin sheaths that cover the neurons. "In addition, a possibility has been raised that GFAP levels could discriminate anti‐AQP4 antibody‐seropositive NMOSD from other demyelinating diseases such as anti‐MOG antibody‐associated diseases." (PMID 32495489, 2020). "Serum neurofilament light chain (sNfL) and serum glial fibrillary acidic protein (sGFAP) are new biomarkers that have been shown to have increased values in demyelinating diseases." (PMID 38002031, 2023). "With reference to pediatric diseases, blood biomarkers NfL and GFAP are increased in children with acute demyelinating disorders and have potential value for the decision who to treat, and to monitor therapeutic responses." (PMID 35665032, 2022). "GFAP is the main component of intermediate filaments of the cytoskeleton of astrocytes, and is usually found upregulated in case of demyelinating diseases." (PMID 35028271, 2022). "In patients with demyelinating diseases, the median CSF GFAP level is 8,601 pg/mL and the median serum GFAP level is 167 pg/mL from NMOSD and MS patient." (PMID 35370870, 2022). "Given that astrocyte injury is thought of as an important early step in brain inflammation and GFAP is implicated in astrocytic functional processes, these findings support the hypothesis that citrullination is important in the pathogenesis of this demyelinating disease." (PMID 25722987, 2015). "Serum GFAP levels could be used as a diagnostic marker for NMOSD, as they are significantly higher in NMOSD patients compared to those in healthy controls and patients with other demyelinating diseases (MS or MOGAD)." (PMID 35370870, 2022). "However, serum NfL was not useful to distinguish NMOSD from other demyelinating diseases, and less sensitive and specific than serum GFAP in identifying and predicting NMOSD relapses." (PMID 35370870, 2022). "In previous Mayo clinic reports, Lennon and her colleagues identified patients with GFAP astrocytopathy with several additional kinds of autoantibody, including NMDAR antibody, AQP4 antibody, and MOG antibody, which suggests an immune encephalitis or demyelinating disorder." (PMID 29755396, 2018).
malignant glioma (17 papers, 2010 to 2025). A grade III or grade IV glioma arising from the central nervous system. "A similar phenomenon has been reported for other proteins and cancers, including loss of glial fibrillary acidic protein and brain fatty acid-binding protein in malignant glioma cell lines compared to tumor tissue." (PMID 26142905, 2015). "In fact, increased GFAP+ EVs have been found in patients with malignant gliomas compared to healthy controls both before and after resection, suggesting that an elevated GFAP+ EV burden reflects the presence of underlying CNS pathology." (PMID 41373835, 2025). "In a recent study of blood‐based biomarkers in patients undergoing surgery and postoperative radiotherapy for malignant glioma, plasma NfL and GFAP were both correlated to preoperative tumor volume." (PMID 39030984, 2024). "Illudin M killed malignant glioma cells as well as primary neurons and astrocytes at similarly low concentrations and destroyed their microtubule and glial fibrillary acidic protein (GFAP) networks." (PMID 36012321, 2022). "In the current study, we specifically examined survivin and GFAP on the surface of serum-derived CD9+ exosomes from patients with recurrent malignant glioma who underwent investigational therapy consisting of active specific vaccination against survivin." (PMID 29383115, 2017). "Here we show that patients with malignant gliomas have circulating exosomes with both survivin and glial fibrillary acidic protein (GFAP) detectable on their surface using imaging flow cytometry." (PMID 29383115, 2017). "The present study used GFAP promoter-modulated expression of the hNIS gene in an experimental model of radioiodine-based treatment for malignant glioma." (PMID 23420532, 2013). "The experiments demonstrated that effective 131I therapy was achieved in the malignant glioma cell lines following the induction of tumor-specific iodide uptake activity by GFAP promoter-directed hNIS gene expression in vitro and in vivo." (PMID 23420532, 2013). "The fact that expression of GFAP and OLIG2 was encountered in older patients harboring SHH-1A and SHH-1B represents a diagnostic pitfall that needs to be considered in the differential diagnosis of malignant gliomas in children and young adults." (PMID 35501487, 2022). "The glial fibrillary acidic protein (GFAP) promoter is an effective tumor-specific promoter for gene expression and thus may be useful in targeted gene therapy of malignant glioma." (PMID 23420532, 2013). "Mice overexpressing transgenic Myc under the GFAP promoter develop malignant gliomas." (PMID 21304179, 2010). "This study demonstrates that patients with malignant gliomas have CD9+/GFAP+/SVN+ and CD9+/SVN+ exosomes that are released into the circulation and that early reductions in their numbers following anti-survivin immunotherapy might be associated with longer progression-free survival." (PMID 29383115, 2017). "Similarly, in human malignant gliomas, the GFAP expression is controlled by methylation." (PMID 23826164, 2013). "In the present study, the number of U87 cells expressing GFAP, β-tubulin III and Galc was significantly increased following the administration of ATRA, confirming the potent differentiation-inducing ability of ATRA in malignant glioma cells." (PMID 25760394, 2015).
Parkinson’s (17 papers, 2009 to 2025). "Both the striatum and the globus pallidus showed increased GFAP immunostaining intensity in response to experimental parkinsonism and PD." (PMID 39576344, 2024).